BORCS7 (BLOC-1 related complex subunit 7)
Description:
As part of the BORC complex may play a role in lysosomes movement and localization at the cell periphery. Associated with the cytosolic face of lysosomes, the BORC complex may recruit ARL8B and couple lysosomes to microtubule plus-end-directed kinesin motor.
Synonyms: C10orf32; FLJ40752
Tractability: PROTAC: ubiquitination databases record sites on it.
Gene: Protein-coding gene on chromosome 10 (102,854,259 to 102,864,961, forward strand). Ensembl gene ENSG00000166275.
Subcellular location: Lysosome membrane
Subcellular location (Human Protein Atlas): Cytosol; Vesicles
Gene Ontology:
Molecular function: protein binding
Biological process: lysosome localization; organelle transport along microtubule; regulation of endosome size; regulation of lysosome size
Cellular component: BORC complex; cytoplasmic side of lysosomal membrane; lysosomal membrane; lysosome
Genetic constraint (gnomAD): Loss-of-function variants: 10 observed, 11.37 expected, observed/expected ratio (o/e) 0.88, 90% interval 0.54 to 1.48. The upper end of that interval is the gene's LOEUF score, 1.48, which puts it in group 6 of 6, group 1 being the genes least tolerant of losing a copy. Missense variants: 106 observed, 102.52 expected, observed/expected ratio (o/e) 1.03, 90% interval 0.88 to 1.22. Synonymous variants: 48 observed, 37.21 expected, observed/expected ratio (o/e) 1.29, 90% interval 1.02 to 1.64.
Homologues: Orthologues: macaque BORCS7 (99% identical), pig BORCS7 (96% identical), mouse Borcs7 (95% identical), rat Borcs7 (95% identical), guinea pig BORCS7 (94% identical), chimpanzee BORCS7 (92% identical), tropical clawed frog borcs7 (86% identical), zebrafish borcs7 (77% identical), Drosophila melanogaster BORCS7 (25% identical), Caenorhabditis elegans blos-8 (21% identical).
Diseases named in the same sentence as BORCS7 in open-access papers:
BORCS7 is named in the same sentence as 7 diseases in open-access papers, as found by Europe PMC text mining. Sharing a sentence is not in itself a finding about the gene and the disease. The quoted sentences say what the papers report.
schizophrenia (4 papers, 2016 to 2023). A major psychotic disorder characterized by abnormalities in the perception or expression of reality. "In the 10q24.32 region, BORCS7, a genome-wide risk gene for schizophrenia, blood pressure, body mass index, and CAD, had the highest PIP of 0.97 in the dorsolateral prefrontal cortex." (PMID 34859065, 2021). "We report altered cis‐regulation of BORCS7, AS3MT, and NT5C2 in association with schizophrenia risk variation, implicating these as genuine schizophrenia susceptibility genes at the locus." (PMID 27004590, 2016). "While not excluding effects on other genes in the region, this study implicates altered neural expression of BORCS7, AS3MT, and NT5C2 in susceptibility to schizophrenia arising from genetic variation at the chromosome 10q24 locus." (PMID 27004590, 2016). "Largest and most consistent effects were observed on BORCS7, AS3MT, and NT5C2, providing functional support for these as genuine susceptibility genes for schizophrenia." (PMID 27004590, 2016).
Stroke (2 papers, 2015 to 2021). Sudden impairment of blood flow to a part of the brain due to occlusion or rupture of an artery to the brain. "Given that both stroke and MDD affect the brain, both RPL31P12 and BORCS7 loci are attractive as candidates conferring genetic liability for both diseases." (PMID 34859065, 2021).
HCMV infection (1 paper, 2020). "Among these proteins, STEAP3, BORCS7, FAM172A, RELL1, and WDR48 were further demonstrated to affect HCMV infection." (PMID 32481657, 2020). "During the late phase of HCMV infection, STEAP3, BORCS7, FAM172A, RELL1 and WDR48 were differentially expressed between Han- and HanUL138del-infected cells, and further functional studies indicated that all of these proteins could affect HCMV infection." (PMID 32481657, 2020).
BORCS7 also shares sentences with these, for which no sentence is quoted: Hypertension (2 papers); malnutrition (1); prostate carcinoma (1); type 2 diabetes (1).